TNF (tumor necrosis factor)
Diseases named in the same sentence as TNF in open-access papers (continued):
Sharing a sentence is not in itself a finding about the gene and the disease.
autoimmune disease (continued). "In this regard, with aging there is an increase in pro-inflammatory cytokines, including IL-6, TNFα and NLRP3 inflammasome, which are associated with age-related diseases such as autoimmune diseases, cancer, and metabolic disorders." (PMID 38265117, 2024). "We have also reported that targeting systemic inflammation with tumor necrosis factor (TNF)-antagonists decreases BPH incidence in autoimmune disease patients and decreases macrophage accumulation in prostate tissues." (PMID 39867899, 2024). "The role of TNF-α and IL-6 in regulating immune system is well-described in inflammatory-mediated disorders, autoimmune diseases or infection." (PMID 38421574, 2024). "ADAM17 has attracted considerable interest as a key enzyme in autoimmune disease pathogenesis since it is responsible for the release of soluble TNF-α." (PMID 39768182, 2024). "TNF-α is a major proinflammatory cytokine upregulated in chronic inflammatory and autoimmune diseases." (PMID 39103899, 2024). "The involvement of TNF-α in the pathogenesis of autoimmune diseases is somewhat confirmed by the effective responses to anti-TNF-α antibody therapy." (PMID 38610653, 2024). "Adalimumab is an anti-TNF agent used in the treatment of autoimmune diseases such as psoriatic arthritis and sarcoidosis." (PMID 39881908, 2024). "Overall, the TNF‐α pathway continues to be a significant research area, offering potential insights into novel therapeutic approaches for various inflammatory and autoimmune disorders." (PMID 39660881, 2024). "TNF-α has been identified as a significant regulator and pathological factor impacting inflammation and autoimmune disease progression." (PMID 38612859, 2024). "The anti-TNFα drug adalimumab stands as a pivotal development in the management of autoimmune diseases, offering substantial benefits to patients suffering from these conditions." (PMID 38846411, 2024). "Mean age was 47 ± 19 years, and 26 (67%) were men; 33 (85%) were immunocompromised, including 15 who had received a solid organ transplant and 7 taking tumor necrosis factor alpha inhibitors for autoimmune diseases." (PMID 39286034, 2024). "These insights elucidate the critical mechanisms by which TNF-α regulates iTreg differentiation and support the therapeutic potential of TNF-α antagonists in treating autoimmune diseases." (PMID 39658797, 2024). "TNF-α is additionally a key inflammatory cytokine associated with RA and SLE among other autoimmune diseases with low TNF-α playing a role in susceptibility as well as in the clinical manifestation of the diseases." (PMID 39689160, 2024). "Originally identified for its role in inducing tumor necrosis, tumor necrosis factor α (TNFα) has recently been recognized for its crucial involvement in autoimmune diseases as a pathological component." (PMID 39512337, 2024). "Th1 cells secrete IL-2, IL-8, IFN-γ, TNF-α, and other cytokines, which mediate cellular immune responses and organ-specific autoimmune diseases." (PMID 38369554, 2024). "Tumor necrosis factor-alpha (TNF-α) is involved in the inflammatory processes of various autoimmune diseases such as RA and Crohn’s disease." (PMID 38962006, 2024). "In the context of autoimmune diseases, we demonstrated that blocking TNFα signaling using anti-TNFα antibodies leads to upregulated IFN-I signaling dynamics, while blocking IFN-I-mediated paracrine signaling using JAKi inhibits TNFα production." (PMID 38596672, 2024). "TNF‐α is involved in various physiological processes and pathological conditions, including infectious and inflammatory diseases, autoimmune diseases, and cancers." (PMID 39660881, 2024). "A high concentration of TNF-α is an indicator of heart disease, cancer, autoimmune diseases, and diabetes." (PMID 38920613, 2024).
autoimmune disease (continued). "Patients with chronic periodontitis presented increased levels of IL-6 and tumor necrosis factor-alpha (TNF-α) in saliva, while elevated levels of IL-6 and TNF-a in this fluid were also associated with chronic infections and autoimmune disorders." (PMID 39795606, 2024). "Research has found that higher TNF-α levels play an important role in the development of certain autoimmune disorders." (PMID 37914104, 2024). "Tumor necrosis factor alpha inhibitors (TNFi) are biological drugs used worldwide to treat various autoimmune disorders." (PMID 39529874, 2024). "TNF-α, as a crucial immune cytokine, plays a significant role in the development and progression of various inflammatory, infectious, and autoimmune diseases." (PMID 38390212, 2024). "Increased levels of proinflammatory markers such as the C-reactive protein (CRP) and interleukin (IL)–6, IL-8, and tumor necrosis factor (TNF)–α are closely associated with active inflammation and disease progression in cardiovascular and autoimmune diseases." (PMID 39499914, 2024). "Although TNF-neutralizing antibodies are commonly used to treat patients with autoimmune diseases (i.e., RA, IBD, and psoriasis), the efficacy of these drugs with respect to human asthma is not shown." (PMID 38540714, 2024). "While the precise relationship between TNF, gut dysbiosis and autoimmune disease is under investigation, our study highlights this as a crucial area for future research." (PMID 39850904, 2024). "Recent studies have even linked probiotics induced production of cytokines such as interleukins IL-1 β, IL-6, interferons IFN and tumor necrosis factor TNF-α, to excessive immunological effects resulting in inflammation or autoimmune disorders." (PMID 38510031, 2024). "TNF- α, as a mediator of autoimmune disease, significantly contributes to the pathogenesis of several chronic inflammatory and rheumatic diseases." (PMID 38335182, 2024). "TNF inhibitors are a class of pharmacologic agents that treat autoimmune disorders by binding TNF to block its interactions." (PMID 39712842, 2024). "There are scattered reports of increased blood levels of inflammatory cytokines (e.g., TNF-α and IL-6) in patients with sarcopenia in comparison to those without sarcopenia, suggesting a close relationship between sarcopenia and autoimmune diseases." (PMID 39600735, 2024). "MS is an autoimmune disease induced by autoreactive T-lymphocytes that is characterized by an imbalance of pro-inflammatory cytokines, such as TNF-α, IFN-γ, IL-2 and lymphotoxin, and regulatory cytokines (e.g., IL-4 and IL-10)." (PMID 39596101, 2024). "The role of TNFα in autoimmune diseases and chronic inflammation has been thoroughly reviewed by Jang and colleagues." (PMID 38338832, 2024). "Elevated TNF-α secretion is thought to play an important role in the pathogenesis of autoimmune diseases, including AS." (PMID 37193965, 2023). "Recent findings, however, suggest a more important and critical function of tumor necrosis factor-alpha (TNF-α) as a pathophysiological component of autoimmune diseases, in addition to its capacity to induce tumor necrosis." (PMID 36767149, 2023). "Potential LCV causes include autoimmune diseases (i.e., RA, SLE, Sjogren, and Henoch–Schönlein purpura), infection, and drug-mediated immune reactions, especially TNF-α inhibitors." (PMID 37175894, 2023). "Inflammatory cytokines such as TNF-α are expressed at high levels in patients with various autoimmune diseases, where they contribute significantly to chronic inflammation." (PMID 36814288, 2023). "IL-1β, IL-8 and TNF-α are the major pro-inflammatory factors, which play significant roles in the development of inflammatory and autoimmune diseases." (PMID 37791345, 2023). "The TNF plays a significant role in the pathogenesis of various inflammatory and autoimmune diseases." (PMID 37047033, 2023).
autoimmune disease (continued). "TNF has been identified as the main regulator of the inflammatory response and is involved in some inflammatory and autoimmune diseases." (PMID 36976991, 2023). "In autoimmune diseases of the CNS, TNF-α is a key inflammatory cytokine that regulates peripheral and local immune responses." (PMID 37483590, 2023). "Paradoxical inflammatory effects of anti-Tumor necrosis Factor-α (anti-TNFα) have been noted most probably because of a disequilibrium in cytokine balance and include exacerbation or initiation of drug-induced autoimmune diseases, and uveitis." (PMID 37589912, 2023). "In the event of infection, patients with autoimmune diseases have dysregulated innate and acquired immune responses that lead to overproduction and overresponse, mediated by pro-inflammatory cytokines such as TNF-α, IL-6, IL-Iβ, IL-17, and IL-18." (PMID 37104352, 2023). "In autoimmune diseases, some cytokines, such as IFN-γ, TNF-α, IL-17, and IL-6, are associated with ILD." (PMID 37089962, 2023). "Adalimumab is a recombinant human monoclonal antibody directed against tumor necrosis factor alpha (TNFα) which has been increasingly used in the management of inflammatory and autoimmune diseases." (PMID 37223151, 2023). "In this context, TNF blockers are considered a great advance in the fight against autoimmune diseases, contributing to their control and providing a good quality of life for patients in most cases." (PMID 36979909, 2023). "High concentrations of TNF-α can contribute to various pathological processes, including inflammaging, autoimmune diseases, and tumors." (PMID 38087369, 2023). "On the other hand, TNF-α is important for the maintenance and regeneration of myelin, and TNF blockers are known to exacerbate symptoms of multiple sclerosis, an autoimmune disease characterized by inflammatory injury to myelin in the CNS." (PMID 38073631, 2023). "The intricate nature of TNF-TNFRs signaling and expression by both leukocytes and by CNS cell types poses some challenges in analyzing therapeutical effects in autoimmune diseases." (PMID 37138340, 2023). "Regarding the regulation of innate immunity, previous research focused on inhibiting the production of proinflammatory factors, such as IL-1, IL-6, and tumor necrosis factor-α (TNF-α), which has proven to be effective in other autoimmune diseases." (PMID 36817420, 2023). "In recent years, TNF antagonists have been used to treat autoimmune diseases and have provided, in many cases, better control and quality of life for related patients." (PMID 36979909, 2023). "For the analyses of incident tinnitus by category of anti-TNFα, 2397 and 9471 patients with autoimmune disorders were selected to the TNFα-FP and TNFα-AB samples, respectively." (PMID 36902722, 2023). "For instance, inhibition of TNF-α is an efficient treatment target in several autoimmune diseases, including IBD and RA." (PMID 37219933, 2023). "Administration of anti‐TNF to patients for the treatment of autoimmune disease leads to reductions in all of these key inflammatory cytokines." (PMID 37382255, 2023). "The level of TNF-α increases in inflammatory diseases, viral and bacterial infections, while it decreases in autoimmune diseases." (PMID 37763806, 2023). "Due to the key role of tumor necrosis factor-alpha (TNF-α) in the pathogenesis of immunoinflammatory diseases, TNF-α inhibitors have been successfully developed and used in the clinical treatment of autoimmune disorders." (PMID 36836166, 2023). "As the important pro‐inflammatory cytokines, IFN‐γ and TNF‐α contribute to the progression of autoimmune diseases, overproduction of inflammatory cytokines can lead to pathological damage of the placenta, which can lead to adverse pregnancy outcomes." (PMID 37771913, 2023).
autoimmune disease (continued). "In patients with SLE and other autoimmune disease, the level of TNF‐α is significantly increased, which destroys the immune balance, promotes the occurrence of inflammatory response, and intimately leads to pathological damage of tissue and organs." (PMID 37771913, 2023). "Anti-TNFα agents are the most studied among the biological therapies not only for women but for men with autoimmune diseases, and they can be considered safe when used during the preconception period, as well as in the early stages of pregnancy." (PMID 36836715, 2023). "In patients with Sjögren’s syndrome, it has been observed that TNF-α and IFN-γ can cause ER stress in the salivary gland acinar cells (an autoimmune disease that destroys exocrine glands)." (PMID 37170213, 2023). "Although CD is a heterogeneous autoimmune disease, the expression levels of five key genes (TNF, BIRC3, ANXA1, TNIP3, and FKBP11) were significantly higher in most CD tissues than that in normal tissues." (PMID 37047025, 2023). "Patients with anti-TNFα had ≥90-day history pre-index (first autoimmune disorder diagnosis) and ≥180-day follow-up post-index." (PMID 36902722, 2023). "In this review, we discuss the role of TNF-α in the pathogenesis of the main autoimmune disorders of the CNS and its significance as a therapeutic target." (PMID 37483590, 2023). "Supportively, some researchers suggested that single nucleotide polymorphisms (SNPs) of proinflammatory cytokines such as IL-1 and TNF-α genes related to periodontitis and autoimmune diseases, especially Behçet’s disease." (PMID 37940896, 2023). "TGF-β and TNF-α are essential for suppressing immune responses and are highly expressed in patients with autoimmune diseases and cancer, indicating that the increase in proinflammatory substances in the colonic mucosa of rats fed 50% CP diet may be linked to autoimmune disorders." (PMID 37107392, 2023). "For example, agents targeting TNF pathway (like adalimumab) have been very effective in the treatment of autoimmune diseases and have been the best-selling biologics on the market." (PMID 36301664, 2022). "Innate immune activation is a common denominator in the pathophysiology of autoimmune diseases, and is many times characterized by increases in immune mediators, such as cytokines like TNFα and IL6, and exaggerated inflammasome activity." (PMID 35246034, 2022). "Perhaps the best example of this is etanercept, a dimeric Fc fusion of human tumor necrosis factor receptor p75 (TNFR2) used as a TNFα sequestrant in the treatment of autoimmune diseases, which contains predominantly sialylated core 1 O-glycans." (PMID 36214107, 2022). "In KEGG pathway analysis, the DE-IGs were mainly enriched in the Th1 and Th2 cell differentiation, Th17 cell differentiation, IL-17 signaling, Toll–like receptor signaling and TNF signaling pathways, and autoimmune diseases." (PMID 35676907, 2022). "Many chronic diseases, such as cardiovascular diseases, cancer, and autoimmune diseases, are related to increased levels of inflammatory factors such as IL-1β, IL-6, tumor necrosis factor (TNF), and C-reactive protein (CPR)." (PMID 36062133, 2022). "T1DM is an autoimmune disease in which pancreatic β cells are destroyed by infiltrating macrophages and by T cells that secrete IL-6, TNF-α, and interferons." (PMID 35669071, 2022). "This suggests that KD exhibits a similar phenotype with autoimmune diseases, characterized by immune system activation of signaling pathways related to IL-1, IL-6, and TNF and the involvement of T/B cells." (PMID 36042431, 2022). "In certain autoimmune diseases, like RA and PsA, activation of osteoclast cells is increased as a result of the inflammation, which promotes the production of TNF and RANK-L." (PMID 35860269, 2022). "In fact, ustekinumab is generally safer in terms of infectious complications than TNF inhibitors, the most commonly used biologics in autoimmune diseases." (PMID 35860015, 2022).
autoimmune disease (continued). "Since TNF-α plays an essential role in the onset of inflammatory symptoms in autoimmune diseases, anti-TNF-α therapies targeting the interaction between TNF-α and TNF-α receptors 1 (TNFR1) and 2 (TNFR2) are attractive measures to treat patients." (PMID 35655291, 2022). "On the other hand, TNF-α participates in the pathological processes of malignancies and autoimmune diseases." (PMID 36358977, 2022). "Some cases of hyperinfection by S. stercoralis have been reported in patients in immunosuppressed states, due to the administration of anti-TNF-α to treat autoimmune diseases." (PMID 36016178, 2022). "Tumor necrosis factor (TNF)-α is a proinflammatory cytokine that plays an important role in the pathogenesis of autoimmune diseases." (PMID 35629365, 2022). "In support with these finding, Kharrazian (2014) had reported that BPA promotes signaling of T cell in autoimmune diseases and can stimulate the macrophage production of TNF-α." (PMID 35554805, 2022). "TNF-α and IL-6 were first discussed in large samples of different autoimmune diseases to evaluate the potential of them as disease markers." (PMID 35911746, 2022). "TNF-α is involved in numerous autoimmune diseases, while anti-TNF-α treatment has also showed great promises as a therapeutic strategy." (PMID 35681462, 2022). "While anti-TNFα has been established as an effective therapeutic approach for several autoimmune diseases, results from clinical trials have uncovered heterogeneous patients’ response to therapy." (PMID 35627163, 2022). "As in other autoimmune diseases, inflammatory TRMs that dominate the bladder mucosal milieu have high expressions of the pro‐inflammatory cytokines including IL‐1β and TNF‐α." (PMID 35470584, 2022). "Tumor necrosis factor α (TNF‐α) inhibitors have shown great success in the treatment of autoimmune diseases." (PMID 35596609, 2022). "An increase in serum levels of IL-6, tumor necrosis factor (TNF)-α, and C-reactive protein (CRP) can generally be observed in older adults and the susceptibility to infection and the prevalence of autoimmune disease converge." (PMID 35100595, 2022). "RA is an autoimmune disorder of the joints in which proinflammatory cytokines, such as TNFα, IL-17A, immune cells and fibroblast-like synoviocytes, attack joints and cause bone deformation." (PMID 35784351, 2022). "Historically known for an integral role in host defense, TNF is recognized more recently for its deleterious effect in several inflammatory and autoimmune diseases, which prompted the development of anti-TNF therapeutics." (PMID 35074627, 2022). "To date, five TNF-α blockers, namely, infliximab, adalimumab, certolizumab pegol, golimumab, and etanercept, have been approved and used for the treatment of autoimmune diseases." (PMID 36505429, 2022). "These macrophages mediate the inflammatory mediators (IL-1β, IL-12, IL-18, IL-23, and tumor necrosis factor-α – TNF-α) in the autoimmune diseases like inflammatory bowel disease." (PMID 36228298, 2022). "Nevertheless, it is important to note that anti-TNF–induced lupus or lupus-like syndromes have been reported in some autoimmune disease patients receiving systemic TNF blockade." (PMID 35486723, 2022). "Taken together, with respect to successful therapy of inflammatory and autoimmune diseases targeting TNF, a future approach will be selective inhibition or activation of one of the two TNFRs." (PMID 35122118, 2022). "TNF-α and its receptors are involved in the pathogenesis of autoimmune diseases, and TNF-α has both the effects of controlling autoimmunity and promoting inflammation." (PMID 35804318, 2022). "TNFα is a major target for treating both ophthalmic and systemic inflammatory and autoimmune disease." (PMID 35998207, 2022).